CD86 (CD86 molecule)
Diseases named in the same sentence as CD86 in open-access papers (continued):
Sharing a sentence is not in itself a finding about the gene and the disease.
lupus nephritis (4 papers, 2012 to 2025). Glomerulonephritis in the context of systemic lupus erythematosus. "B. fragilis mitigated lupus nephritis symptoms by modulating CD1d and CD86 expression in B cells." (PMID 40534849, 2025). "Anti-CD86 (1D1), a mAb that recognizes both human and mouse CD86, was used in the CGVHD-induced experimental lupus nephritis model." (PMID 33123125, 2020).
metastatic tumors (4 papers, 2020 to 2024). "Based on our data, the detected elevated populations of CD80+ and CD86+ lymphocytes in the patients with metastatic disease can also be included in the group of markers for CRC." (PMID 39456247, 2024).
monocytic leukemia (4 papers, 2017 to 2022). "As THP-1 is a monocytic leukemia-derived cell line, it can be speculated that the failure to upregulate CD86 for further T cell activation could be an immune evasion mechanism typical for some types of cancer." (PMID 35625726, 2022). "Upregulation of ITGAM and CD86 following LSD1 inhibition was correlated with myeloid differentiation, inhibition of human monocytic leukemia cell proliferation, and sensitization of AML cells to all-trans-retinoic acid." (PMID 31740623, 2019). "The frequencies of CD86+ and CD163+ cells and expression levels of these markers as well as the cytokines IL-12 and IL-10 were measured in THP-1- (human monocytic leukemia cell) derived macrophages." (PMID 30276219, 2018).
ovarian tumor (4 papers, 2021 to 2025). "In a treatment-naïve ovarian tumor-bearing mouse model, upfront combination therapy effectively promoted an anti-tumor microenvironment, as evidenced by an increase in CD86+CD206- macrophage cells and a concomitant decrease in CD86-CD206+ macrophage cells." (PMID 41315319, 2025). "However, even with these limits, we observed that the treatment of humanized ovarian tumor-bearing mice by murlentamab monotherapy tended to increase CD86+ blood cells and strongly decreased CD163+ blood cells, signing a monocyte/macrophage orientation towards an M1 anti-tumor profile." (PMID 33924378, 2021). "Immunofluorescence assays identified EOC ascites spheroids as multicellular structures containing ovarian tumor cells (PAX8+Ki67+) and numerous lymphocytes, such as TAMs (CD68+CD206+, CD68+CD86+), T cells (CD8+), DCs (CD11c+) and NK cells (CD56dim, CD56bright)." (PMID 39198883, 2024).
prostate carcinoma (4 papers, 2009 to 2023). A carcinoma that arises from epithelial cells of the prostate gland. "The majority of the studies provided information for the following surrogate markers: CD14 (prostate cancer 8/17 studies, RCC 7/12 studies), HLA-DR (prostate cancer 11/17, RCC 7/12), CD86 (prostate cancer 11/17, RCC 8/12), and CD83 (prostate cancer 9/17, RCC 9/12)." (PMID 21533099, 2011).
rectal cancer (4 papers, 2020 to 2023). A primary or metastatic malignant neoplasm that affects the rectum. "Among them, CHRDL2 and CD86 were associated with both colon and rectal cancers, with consistent direction." (PMID 37726845, 2023). "TCM from both mock-irradiated (p = 0.007) and irradiated (p = 0.001) rectal cancer tissue significantly enhanced LPS-induced expression of CD86." (PMID 33540635, 2021). "Together, these results demonstrate significant correlations between CD86 expression and t/sCD8+ cell density in rectal cancer after nCRT and could potentially have clinical implications for combining ICIs and nCRT." (PMID 36428666, 2022). "There was an inverse correlation between VEGF-C and CD86 (r = −0.9276, p = 0.01) and CD11c (r = −0.8857, p = 0.03) in DCs treated with TCM from irradiated rectal cancer tissue." (PMID 33540635, 2021).
renal carcinoma (4 papers, 2019 to 2025). A carcinoma arising from the epithelium of the renal parenchyma or the renal pelvis. "In renal cancers, the main contributors to PC-1, the axis separating healthy and sick – were the CD86, TIGIT, ICOS, and BTLA genes." (PMID 40788962, 2025). "when neutrophils were co-cultured with PD-L1 knockout renal cancer cells, the CSF2-induced shift toward the N2 phenotype was partially attenuated, with decreased CD163/CD206 expression and a partial recovery of CD54/CD86 levels compared to co-culture with wild-type tumor cells." (PMID 41216204, 2025). "Current major immunotherapies in cancer, including renal cancer, are based on the blocking by specific monoclonal antibodies of the binding of the B7 immune checkpoint proteins CD80/B7-1 and CD86/B7-2, and PD-L1/B7-H1 and PD-L2/B7-DC, with their co-receptors CTLA-4 and PD-1, respectively." (PMID 35563753, 2022). "In contrast, no significant changes were observed in the expression of CD86 in macrophages co-cultured with hypoxia-treated renal cancer cells respect to those exposed to normoxia." (PMID 30788287, 2019).
skin sensitization (4 papers, 2011 to 2025). An immunological response to previous exposure to a substance which results in an inflammatory skin reaction. "The upregulation of CD54 together with CD86 are the key readout parameters of the h-CLAT aiming to mimic dendritic cell activation in order to predict skin sensitization." (PMID 36674966, 2023). "After 24-hour incubation, variations of the RFI as an index of skin sensitization were determined by measuring the fluorescence intensity of CD86 and CD54 immune markers." (PMID 21826143, 2011). "The baseline expression of CD86 in the dendritic cells distributed within the epidermal layer highlights the ability of iPSC-DC to participate in T-cell activation, a critical step in the immune response during skin sensitization." (PMID 40336952, 2025).
acute GVHD (3 papers, 2018 to 2025). "In acute GVHD (aGVHD) patients, there is a marked upregulation in the expression of CD86 (an activation marker) and CD20 (a marker of mature B cells), which mirrors the changes seen in B cells during infections." (PMID 39946832, 2025). "In contrast, in biopsies from inflamed skin taken during acute GVHD, the increase in HLA class II-expressing cells was not caused by macrophages, but by an increase in inflammatory DCs, because HLA class II-positive cells expressed CD11c, CD40, CD54, and CD86 in separate stainings." (PMID 29535719, 2018).
adenoma (3 papers, 2020 to 2025). A neoplasm arising from the epithelium. "In the CRA group, patients with adenomas ≥1 cm in diameter had higher expression of CD163+ and CD86+ TAMs than those with smaller adenomas (P < 0.05)." (PMID 41395618, 2025). "Multiple linear regression analysis showed that in colorectal adenomas measuring ≥ 1 cm, expression of CD163+ and CD86+ TAM was significantly greater than in adenomas <1 cm (P < 0.05), Expression of CD163+ TAM was notably higher in obese patients with CRC." (PMID 41395618, 2025). "Multivariate regression further confirmed this relationship: CD163+ TAMs (β = 7545.441, 95% CI: 5575.552 ~ 9515.329) and CD86+ TAMs (β = 4488.870, 95% CI: 3477.967 ~ 5499.773) were significantly increased in patients with larger adenomas." (PMID 41395618, 2025). "Although IL-1β levels gradually increase with the transformation of healthy colon tissue to adenoma and further to CRC56, tumor-associated ILCs displayed CD86 expression only in three out of thirteen CRC cases analyzed." (PMID 32341343, 2020). "Our univariate analysis indicated that patients with adenomas ≥1 cm or multiple adenomas exhibited significantly higher expression of both CD163+ and CD86+ TAMs." (PMID 41395618, 2025).
allergic rhinitis (3 papers, 2013 to 2025). Inflammation of the nasal mucous membranes caused by an IgE-mediated response to external allergens. "Shikonin has been shown to alleviate excessive Th2 cell activation in rat models of allergic rhinitis by reducing the expression of co-stimulatory molecules CD80 and CD86 on dendritic cells while concurrently reducing the circulating levels of IL-4 in peripheral blood." (PMID 41560747, 2025).
breast tumor (3 papers, 2022 to 2025). "Next, we investigated the association between CD68, CD163, CD86, and PD-L1 expression and the clinicopathological features of primary breast tumors." (PMID 40510346, 2025). "Next, we analyzed the impact of CD68, CD163, CD86, and PD-L1 expression on recurrence-free survival (RFS), defined as the time between the initial diagnosis of the primary breast tumor and cerebral progression." (PMID 40510346, 2025).
brucellosis (3 papers, 2017 to 2021). Brucellosis is a bacterial infection that spreads from animals to people via unpasteurized dairy products or by exposure to contaminated animal products or infected animals. "In vivo, IL-6, TNF-α, and CD80/CD86 are required for activation of the interferon gamma-producing CD4+ Th1 and CD8+ cytotoxic T cells, a protective response induced by the host against brucellosis." (PMID 34992597, 2021). "In vivo, IL-6, TNF-α, and CD80/CD86 are required in the activation of the interferon gamma-producing T CD4+ helper type 1 (Th1) and T CD8+ cytotoxic, a protective response induced by the host against brucellosis." (PMID 32765455, 2020). "Moreover, 3-MA restored CD80 and CD86 expression levels on M1 macrophages, and CD163 and CD206 expression levels on M2 macrophages in brucellosis patients." (PMID 28659924, 2017).
Cerebral ischemia (3 papers, 2020 to 2024). Restriction of arterial blood supply to the brain associated with insufficient oxygenation to support the metabolic requirements of the tissue. "Furthermore, GW4869 administration also alleviates neuroinflammation post cerebral ischemia, ascertained by the decrease of CD86 and increase of CD206 in all test brain regions in GW4869-treated groups vs. DMSO-treated groups." (PMID 32117296, 2020). "We found that MCAO significantly enhanced the expression of CD86 and inhibited that of CD206, in ischemic infarction, ischemic penumbra, and hippocampus in the ischemic brain hemisphere, suggesting neuroinflammation is induced by focal cerebral ischemia." (PMID 32117296, 2020).
cervical squamous cell carcinoma (3 papers, 2021 to 2024). A squamous cell carcinoma arising from the cervical epithelium. "The results showed that low CD86 expression was associated with bladder urothelial carcinoma, cervical squamous cell carcinoma, and endocervical adenocarcinoma." (PMID 37064861, 2023). "In cervical squamous cell carcinoma (CESC), ICOS, KIR2DL4, TNFSF9, and CD86 function in immune activation and display a negative association with METTL3 expression." (PMID 39199429, 2024).
Chagas disease (3 papers, 2018 to 2022). A parasitic infection caused by Trypanosoma cruzi. "Although the role of CD80 and CD86 co-stimulatory molecules is already known to activate adaptive immunity, the involvement of these molecules in Chagas disease is poorly studied." (PMID 35665256, 2022). "CD80 and CD86 co-stimulatory molecules in monocytes from patients with Chagas disease following induction by T. cruzi recombinant antigens are important for the activation of T cells." (PMID 29599775, 2018). "As detailed above, patients with the IND clinical form of Chagas disease show a higher expression of CD86 than CD80 co-stimulatory molecules by all monocyte subsets." (PMID 29599775, 2018). "In addition, we evaluated the main cytokines produced by total CD4+ T cells after anti-CD80 or anti-CD86 antibody blockade from PBMC cultures of Chagas disease patients and healthy individuals." (PMID 35665256, 2022). "Ultimately, we aimed to characterize the functional-phenotypic profile of monocyte subsets and understand the CD80/CD86 co-stimulatory expression by monocyte subsets in the protective and/or regulatory immunity against T. cruzi infection to further understand Chagas disease progression." (PMID 29599775, 2018). "In Chagas disease, it was observed that there was a higher frequency of CD80+ monocytes in IND and CARD patients and a lower frequency of CD86+ monocytes only in the CARD form." (PMID 35665256, 2022). "This study advances the current knowledge about the immunoregulatory mechanisms mediated by CD86, CTLA-4, and by Treg cells in Chagas disease." (PMID 29599775, 2018). "Using flow cytometry, we evaluated the effect of in vitro stimulation with Trypanosoma cruzi antigens on the expression of the co-stimulatory molecules CD80 and CD86 in different monocyte subsets of patients with IND and CARD clinical forms of Chagas disease." (PMID 29599775, 2018). "Through comparing the proportion of CD28 and CTLA-4 ligands in each lymphocyte subsets between patients with Chagas disease, we observed a higher proportion of CD28 on CD8+ Treg cells only after anti-CD80 blockade from CARD in comparison with anti-CD86 blockade and to IND group." (PMID 35665256, 2022). "However, little is known about monocytes subsets in Chagas disease and the influence of CD80 and CD86 co-stimulatory expression in the modulation of the immune response in Chagas patients." (PMID 29599775, 2018). "Many studies have demonstrated the functional role of CD80, CD86, CTLA-4, and CD28 receptors in different pathological settings, yet little is known about the role of these co-stimulatory molecules in Chagas disease patients." (PMID 30405039, 2018).
chronic obstructive pulmonary disease (3 papers, 2018 to 2025). A chronic and progressive lung disorder characterized by the loss of elasticity of the bronchial tree and the air sacs, destruction of the air sacs wall, thickening of the bronchial wall, and mucous accumulation in the bronchial tree. "Human moDCs differentiated from monocytes of chronic obstructive pulmonary disease (COPD) patients expressed increased levels of CD80, CD86 and IFN-α as compared with those of healthy individuals." (PMID 41306974, 2025).
colon adenocarcinoma (3 papers, 2020 to 2022). "Whereas, the TCM from colonic adenocarcinoma significantly inhibited CD54 (p = 0.011), HLA-DR (p = 0.013), CD86 (p = 0.021), CD83 (p = 0.018) and PD-L1 (p = 0.006) compared to LPS-induction in background media alone, cRPMI (+)." (PMID 32552799, 2020).
coronary artery disease (3 papers, 2021 to 2025). "The expression of CD86 on dendritic cells was shown to be up-regulated in patients with coronary artery disease." (PMID 33613306, 2021). "As expected, levels of several EV antigens (CD8, CD8, CD1c, CD25, CD62P, CD42a, CD86, CD44) increased in subjects displaying both OD and established cardiac disease (coronary artery disease, or chronic heart failure), as compared with those with only OD or cardiac disease." (PMID 39702460, 2024).
dermatitis (3 papers, 2010 to 2024). An inflammatory process affecting the skin. "Pathways, including OX40-OX40L and CD28-CD80/CD86, have been found to play an important role in skin disorders and to be involved at different stages of CD8 T cell activation/differentiation but as yet have not been linked to MC-CD8 T cell interactions." (PMID 36675078, 2023). "6-MC (responsible for photocontact dermatitis reactions) induced a dose-dependent increase in CD86 expression after irradiation (>40% ΔCD86)." (PMID 21203464, 2010).
encephalitis (3 papers, 2018 to 2023). An acute inflammatory process affecting the brain parenchyma. "The serum of patients with LGI1 encephalitis had reduced levels of CD28, ICOS-L, PDCD1 (all p < 0.05), and CD86 (p < 0.01), but higher levels of ICOS (p < 0.05) and PD-L2 (p < 0.001) were detected." (PMID 37644514, 2023). "A few days later (days 12–16), when the mice develop clinical signs of encephalitis, the expression of chemokines in the eye peaks and there is a clear increase in CD45, as well as increased expression of MHC, CD80, CD86, and CD68." (PMID 29802245, 2018).
epilepsy (3 papers, 2021 to 2024). A brain disorder characterized by episodes of abnormally increased neuronal discharge resulting in transient episodes of sensory or motor neurological dysfunction, or psychic dysfunction. "Then, we measured the levels of Arg-1, CD68, iNOS and CD86 in the hippocampus 24 hours after epilepsy modeling." (PMID 35356535, 2022). "mRNA expression of iNOS and CD86 (both markers of the M1 subtype) was increased markedly in VPA-resistant epilepsy, whereas expression of Arg-1 and CD206 (both markers of the M2 subtype) was decreased significantly in VPA-resistant epilepsy compared with VPA-sensitive epilepsy." (PMID 34497517, 2021).
follicular lymphoma (3 papers, 2018 to 2024). Follicular lymphoma is a form of non-Hodgkin lymphoma characterized by a proliferation of B cells whose nodular structure of follicular architecture is preserved. "For example, upregulation of CD80/CD86 and other costimulatory and adhesion molecules leads to increased APC activity and enhanced triggered T cell responses in follicular lymphoma (FL)." (PMID 31195368, 2019). "Follicular lymphoma or mantle cell lymphoma also showed an increased expression of CD80 and/or CD86 in response to TLR9 agonist." (PMID 29805758, 2018).
gestational diabetes mellitus (3 papers, 2018 to 2021). "Despite the general view, recent studies in humans have claimed that gestational diabetes mellitus (GDM) causes temporary M1 proinflammation in HBCs, with a trend for increasing CD86 expression." (PMID 32265918, 2020).
helminth infection (3 papers, 2014 to 2022). "A Th2 immune response is desirable in helminth infection, but as the ileum is not the site of infection, it was surprising to observe the up-regulation of genes, including CD86, Ovar-DRB1, IL1RL1 and IL-6, that polarize the immune response towards a Th2 response." (PMID 35576023, 2022). "Thus, a lack of detectable expression of MHC-II in many infiltrating myeloid cells, along with a low/diminished level of the costimulatory molecules, CD80, CD86 and OX40L, suggests a defect in the maturation of these cells in the CNS environment during helminth infection." (PMID 25013939, 2014). "In MS patients with helminth infections, there is a compensatory abundance of IL-10-producing B cells through a mechanism that is largely dependent on the Inducible T cell costimulator ligand (ICOSLG)-pathway and not on the CD40, CD80 or CD86 pathways." (PMID 34122439, 2021).
histiocytic sarcoma (3 papers, 2016 to 2025). An aggressive malignant neoplasm with a poor response to therapy, usually presenting as stage III/IV disease. "CD80 and CD86 expressing cells were further quantified by in situ hybridization and compared with data from three cases of canine histiocytic sarcoma (HS), a malignant tumor variant originating from antigen-presenting interstitial dendritic cells." (PMID 39619201, 2024). "Previous results showed elevated mRNA expression of cell surface antigens, including MHC class II and CD86, in tumor tissue from dogs with histiocytic sarcoma." (PMID 26901565, 2016). "Thus, the present study aimed to investigate the effects of CD80 and CD86 in histiocytic sarcoma (HS), a rare and progressive malignancy in dogs and to elucidate the status of the interferon-I pathway." (PMID 40271486, 2025). "In particular, CTLA-4 may play an important role in antitumor activity in canine histiocytic sarcoma because of the high expression of the ligand CD86, which can bind to CTLA-4." (PMID 26901565, 2016). "Finally, we tested the hypothesis whether canine histiocytic sarcoma (HS), a malignant canine tumor of interstitial DC origin that does not undergo regression but usually progresses with poor prognosis, lacks CD80 and CD86 expression." (PMID 39619201, 2024).
Hodgkins lymphoma (3 papers, 2019 to 2021). A heterogeneous group of malignant lymphoid neoplasms of B-cell origin characterized histologically by the presence of Hodgkin and Reed-Sternberg (HRS) cells in the vast majority of cases. "Remarkably, the differences in activated B cells (CD19+/CD80+ and CD18+/CD86+) persisted when 14 HIV(+) AHCT recipients with Hodgkin lymphoma were compared directly to HIV(-) AHCT recipients by Wilcoxon rank sum analysis (p<0.0185)." (PMID 34539628, 2021). "The interference of vaccinia virus-infected cell culture supernatant was confirmed by flow cytometry using the CD80- and CD86-positive human cell line KM-H2 (Hodgkin lymphoma) and soluble recombinant CTLA4-Fc." (PMID 30918073, 2019).